CCR2 (C-C motif chemokine receptor 2)
Diseases named in the same sentence as CCR2 in open-access papers (continued):
Sharing a sentence is not in itself a finding about the gene and the disease.
lung carcinoma (46 papers, 2013 to 2025). "We investigated the role of the CCR2/MCP-1 pathway in MDSC-associated tumor progression in murine lung cancer models." (PMID 33322474, 2020). "In this report, lung cancer cells breached the vascular basement membrane and endothelial barrier to metastasize to the left atrium via the pulmonary vein, a process potentially linked to CC-chemokine receptor 2 (CCR2) signaling by monocytes." (PMID 39328239, 2024). "We planned to investigate the role of the CCR2/MCP-1 pathway in MDSC-associated tumor progression in murine syngeneic lung cancer models but undertook some basic characterization of the main mouse strain to be used, namely mice lacking the gene for CCR2 (CCR2KO)." (PMID 33322474, 2020). "A previous study highlighted that the reciprocal communication between TAMs and lung cancer cells through the CCL2/CCR2 signaling pathway is a significant mechanism underpinning TAM-driven facilitation of lung cancer proliferation and dissemination." (PMID 40417000, 2025). "The discovery of 106 immune signatures, particularly five key associations such as CD25 on IgD- CD24- cells in SCLC and CCR2 on monocyte cells in LUSC, enriches our understanding of these cells’ causal involvement in lung cancer." (PMID 38962009, 2024). "Tumor macrophage infiltration and CCR2 expression have been found to correlate with both tumor stage and metastasis in human lung cancer samples." (PMID 39114657, 2024). "This is consistent with a recent study that demonstrated CCR2 antagonism similarly downregulated MMP-9 in lung cancer cells, resulting in reduced cellular motility." (PMID 38228786, 2024). "CXCR2 and CCR2 are the most extensively studied chemokine receptors in preclinical studies of lung cancer." (PMID 39114657, 2024). "In a mouse model of lung cancer, it was found that knockout of the CCR2 gene or use of the CCR2 inhibitors inhibited the recruitment of TAMs and promoted their polarization into M1 phenotype, ultimately inhibiting the progression of lung cancer." (PMID 36903624, 2023). "In another study, Abd-Rabou and Ahmed showed that the use of CCR2 inhibitor (CR) nanotreatments on the A549 lung cancer cell line increases the apoptosis ratio." (PMID 37325423, 2023). "Numerous studies have demonstrated that CCR2 participates in the development, especially the infiltration of the immune cells in lung cancer." (PMID 35529878, 2022). "It was demonstrated that CCR2 and CXCR1 signaling played a critical role in the cross-talk between tumor-associated macrophage and lung cancer cells." (PMID 35529878, 2022). "CCR2 induces macrophage and cancer cell crosstalk, an essential mechanism for driving lung cancer progression." (PMID 36033829, 2022). "Another study is consistent with our results, showed that infusion of CCR2 gene‐modified effector T cells enhanced anti‐lung cancer response in vivo." (PMID 33949150, 2021). "One study stressed the involvement of CCL-2/CCR-2 signalling in tumour progression and metastasis in lung cancer patients." (PMID 34336101, 2021). "IHC with antibody against F4/80 was performed to confirm the induction of macrophage infiltration, which can be promoted by up‐regulation of ERα expression in lung cancer cells, and can partly be blocked by treatment with CCR2 antagonist or fulvestrant." (PMID 32356397, 2020). "Experimental lung tumor models, in vitro TAMs-tumor cells, co-culture models, and human lung cancer biopsies demonstrated that CCL2/CCR2 signaling is one of the central signaling pathways involved in lung cancer growth and metastasis." (PMID 32219066, 2020). "Like our results, some authors indicated that the disruption of CCL2/CCR2 chemokine signaling has the ability to suppress A549 lung cancer cell proliferation and invasion." (PMID 31350989, 2019). "An intravenous injection of mouse lung carcinoma cells induced CCR2-independent local accumulation of IMs as well as CCR2-dependent recruitment of circulating monocytes into lungs." (PMID 30597969, 2018).
lung carcinoma (continued). "Our results suggested that the blockade of the CCR2 pathway inhibited the viability, motility and invasion of CCR2-positive human A549 lung cancer cells in vitro." (PMID 28424406, 2017). "A previous study showed that bidirectional cross talk between TAM and lung cancer cells through CCL2/CCR2 signaling is a major mechanism of the TAM-mediated promotion of lung cancer growth and metastasis." (PMID 29207614, 2017). "Intravenously injected HUMSCs have been shown to migrate to lung cancer after 24 hours via MCP-1/CCR2 transduction cascade." (PMID 27594905, 2016). "This cascade consists of overexpression of MCP-1 on lung cancer A549 cells and expression of its receptor CCR2 on the surface of HUMSCs." (PMID 27594905, 2016). "In the present study, we have demonstrated both the feasibility and advantages of CD8+ T cells double-transfected to express WT1-specific TCR and CCR2 for the treatment of at least some human lung cancers." (PMID 23441216, 2013). "Interestingly, chemotherapy including cisplatin has been shown to promote secretion of MCP-1, recruit inflammatory monocytes enriched with the receptor of MCP-1, CCR2, forming pre-metastatic niches, thus promoting distant metastasis in breast and lung cancer." (PMID 36941406, 2023). "Also, CCR2 inhibitor can suppress CCL2-mediated lung cancer cell invasion by downregulating MMP-9 expression." (PMID 37325423, 2023). "Recently, more studies revealed that CCR2 is involved in the ERα (Estrogen receptor α)-induced lung cancer cell invasion by macrophage infiltration mechanism and might be an essential component of cancer immunotherapy." (PMID 35529878, 2022). "Until recently, biological functions of CCR2 in lung cancer had yet to be established." (PMID 36033829, 2022). "CCR2 is the receptor for CCL2 which induces monocyte infiltration in tumors including lung cancer; therefore, MAFB may be a potential indicator for monocyte infiltration." (PMID 36077342, 2022). "In addition, the cross-talk between macrophages and cancer cells through CX3CR1 and CCR2 is the basic mechanism resulting to lung cancer." (PMID 35833114, 2022). "A subsequent study demonstrated that inhibition of recruited macrophages by blockade of CCL2/CCR2 signaling did not attenuate lung cancer progression, as CCR2-deficient mice showed similar tumor growth rate compared to wild-type mice." (PMID 33763066, 2021). "Furthermore, lung carcinogens are highly inflammatory and studies in Tunisia, for example, identified alterations in inflammatory genes- TNF-α, IL8, IL17A, IL17F, CCR2, and VDR Fok1 (rs2228570) and ApaI (rs7975232) that predispose to lung cancer." (PMID 33659210, 2020). "Similarly, homing ability of MSCs was suppressed after either knocking down the expression of MCP-1 in lung cancer cells or blocking CCR2 expressed on the surface of MSCs, indicating the important role of MCP-1/CCR2 axis in the tropism of MSCs to lung tumors." (PMID 28798777, 2017). "Co-introduction of functional CCR2 successfully enhanced in vivo anti-lung cancer reactivity mediated by infused double-transfected effector T cells, notably in the phase immediately after the start of therapeutic infusion, reflecting the increased tumor trafficking activity in response to CCL2." (PMID 23441216, 2013). "Introduction of the CCL2/CCR2 axis successfully potentiated in vivo anti-lung cancer reactivity mediated by CD8+ T cells double gene-modified to express WT1-specific TCR and CCR2 not only via CCL2-tropic tumor trafficking, but also CCL2-enhanced WT1-responsiveness." (PMID 23441216, 2013). "Therefore, interventions of CCR2 expression and M2 polarization TAMs may be potential options for the treatment of lung cancer." (PMID 38111060, 2023). "Therefore, the role of CCR2 in lung cancer requires further investigations." (PMID 36033829, 2022). "Therefore, targeting CCR2 with CAS445479‐97‐0 may be an attractive therapeutic strategy for patients with lung cancer." (PMID 34464477, 2021).
lung carcinoma (continued). "Co-culturing macrophages with lung cancer cell lines can upregulate CCR2/CCL2 and CX3CR1/CX3CL1 in both cancer cells and macrophages, playing a central role in lung cancer growth and metastasis." (PMID 40264773, 2025). "Overall, CXCR2, CXCR4, CCR2 are currently the most extensively studied chemokine receptors in NSCLC and are considered potential biomarkers for lung cancer." (PMID 39114657, 2024). "Anja Schmall found that the tumor-associated crosstalk between macrophages and cancer cells via the CCR2 and CX3CR1 signaling pathways directed the lung cancer growth and metastasis." (PMID 38514488, 2024). "The manifestation of an assemblage of IL-6 and IL-10 or CCR-2, CCL-2 connects to a shoddy projection in patients with lung cancer." (PMID 34336101, 2021). "Expression of CCL2, CCR2 or in combination with IL6 and IL10 correlates with a worse prognosis in lung cancer patients." (PMID 32219066, 2020). "IL10 also drives in vivo lung cancer growth and metastasis by upregulating the CCL2/C-C motif chemokine receptor 2 (CCR2) and C-X-C motif chemokine ligand (CXC3CL1)/C-X3-C motif chemokine receptor 1 (CX3CR1) axis in macrophage-tumor cell crosstalk." (PMID 32219066, 2020). "Recently, we reported that CCR2 transduced tumor antigen-specific CD8+ T cell trafficking by CCL2 expression in lung cancer cells, which potentiated its in vivo anti-lung cancer reactivity." (PMID 28424406, 2017). "We recently provided evidence that macrophage and cancer cell cross talk via CCR2 and CX3CR1, a fundamental mechanism driving lung cancer." (PMID 26413839, 2015). "In the present study, we examined in detail the anti-lung cancer functionality mediated by double-transfected CD8+ T cells to express WT1-specific TCR and CCR2 against LK79 cells, both in vitro and in vivo." (PMID 23441216, 2013). "Next, using a therapeutic xenografted mouse model, we examined in vivo anti-lung cancer reactivity mediated by infused effector cells double-transfected to express both WT1-specific TCR and CCR2." (PMID 23441216, 2013). "Bidirectional crosstalk between macrophages and tumor cells through CCR2 and CX3CR1 signal transduction might be the driving mechanism of lung cancer." (PMID 36090899, 2022). "Interestingly, the estrogen receptor α promotes cancer cell invasion via the increase of and cross-talk with infiltrated macrophages through the CCL2/CCR2/MMP9 and CXCL12/CXCR4 signaling pathways at least in lung cancer." (PMID 34833360, 2021). "Together, the interactions between lung cancer cells and macrophages through ERα/CCL2/CCR2/MMP9 and CXCL12/CXCR4 pathways could promote the NSCLC progression." (PMID 32356397, 2020). "Interestingly, in our research, we found that CCR2 was low‐expression in LUAD, which seemed to elucidate why CCR2 inhibitors have no cytotoxicity on the A549 human lung cancer cell line." (PMID 33949150, 2021).
multiple sclerosis (46 papers, 2005 to 2026). A progressive autoimmune disorder affecting the central nervous system resulting in demyelination. "Other studies showed that CCR2 is one of the most prominent chemokine receptor associated with neuro-inflammatory diseases such as multiple sclerosis and experimental autoimmune encephalomyelitis." (PMID 23977941, 2013). "In addition, CD4+CCR5+CCR2+ T cells are found in cerebrospinal fluid associated with episodes of relapse in multiple sclerosis, and these cells demonstrate an enhanced ability to migrate across a model of the blood-brain barrier." (PMID 29469805, 2018). "In the CCR2 V64I polymorphism, although this amino acid change is conservative, various studies have shown that the 64I allele may be a protective factor in immune-mediated diseases like sarcoidosis and multiple sclerosis." (PMID 17417600, 2007). "The significance of CCL2 and CCR2 in MS is enigmatic because CCL2 levels are consistently decreased in the cerebrospinal fluid of pwMS despite abundant expression within lesioned multiple sclerosis tissues." (PMID 37893243, 2023). "CCR2 and CCL2 have been consistently associated with a pathogenic role in BBB breakdown in patients with multiple sclerosis." (PMID 37056770, 2023). "To date, studies on CCR2 in the central nervous system have mainly focused on multiple sclerosis, Alzheimer's disease, and ischemic stroke." (PMID 36566220, 2022). "In experimental autoimmune encephalomyelitis (EAE), a common animal model of multiple sclerosis, CCR2 expression is increased at both the onset and peak of the disease and is associated with prognosis." (PMID 36566220, 2022). "Scores of studies have been made on the influence of CCR2 and its ligands on various inflammatory diseases of the central nervous system, covering multiple sclerosis (MS), Alzheimer’s disease, and ischemic stroke." (PMID 35246016, 2022). "CCL2 and its receptor CCR2 are induced and take part in a multitude of neurodegenerative diseases like Alzheimer’s disease, multiple sclerosis, and ischemic brain injury." (PMID 35246016, 2022). "Many chemokine receptors such as CCR1, CCR2, CCR5 and CXCR3 have all been implicated in the pathophysiology of multiple sclerosis and rheumatoid arthritis." (PMID 34804061, 2021). "Many of these chemokine receptors are altered in multiple sclerosis patients, who show high levels of CCR2, CCR5, CXCR376." (PMID 33479266, 2021). "In the CNS, it has been shown that CCR2 is expressed in microglia and is upregulated under pathological conditions such as multiple sclerosis, Alzheimer’s disease, and traumatic brain injury." (PMID 24252211, 2013). "In particular, CCR2 and CCR5 and their ligands have been implicated in the pathophysiology of a number of diseases, including rheumatoid arthritis and multiple sclerosis." (PMID 22479344, 2012). "CCR2 and CX3CR1 have been implicated as disease modifiers in EAE, a model for the inflammatory aspects of multiple sclerosis." (PMID 21060874, 2010). "It has been shown that CCL2/CCR2 signaling is upregulated and plays a role in the pathogenesis of neurodegenerative disorders, such as Alzheimer’s disease, multiple sclerosis, HAND, and in the experimental autoimmune encephalomyelitis, a murine model for inflammatory demyelinating diseases." (PMID 34764955, 2021). "The MCP-1/CCR2 chemokine axis is an important mediator of the migration of monocytes, memory T lymphocytes, and natural killer cells into affected areas in diseases such as multiple sclerosis, rheumatoid arthritis, type 2 diabetes, and Alzheimer’s disease." (PMID 24303068, 2013). "Among them, CCL2 is the most potent activator of CCR2 signaling, and the upregulation of CCR2 by CCL2 is associated with cancer metastasis, relapse, and inflammatory diseases in the central nervous system, including multiple sclerosis, Alzheimer’s disease and ischemic stroke." (PMID 35570218, 2022).
multiple sclerosis (continued). "Of note, in a recent study analyzing CNS monocyte infiltration in the multiple sclerosis EAE model and using similar CCR2 reporter mice, the same roundish/elongated morphology of infiltrating CCR2+ monocytes was detected." (PMID 28320442, 2017). "Various chemokine receptors, such as CCR2 with the ligand MCP-1 and CXCL2 with multiple ligands, such as Groα, Groβ and IL-8, are up-regulated in brain lesions of trauma, ischemia, and multiple sclerosis (MS)." (PMID 24691121, 2014). "CCR2 on monocytes is downregulated with most inflammatory conditions in vitro and in vivo, including TNF-α or LPS treatment as well as in atherosclerotic plaques and multiple sclerosis lesions." (PMID 23922698, 2013). "To investigate monocyte trafficking in vivo, we generated red fluorescent protein (RFP)-CCR2 knock-in mice, crossed them with CX3CR1-GFP mice, and analyzed them in models of sterile peritonitis and multiple sclerosis using flow cytometry and evaluation of tissue sections." (PMID 21060874, 2010). "Expression of CCR2, CXCR3 and CCR4 on CD4+ T or CD8+ T cells in blood and cerebrospinal fluid (CSF) for multiple sclerosis (MS) was measured by 3-color flow cytometry, and compared to blood from healthy controls and CSF from patients with other inflammatory neurological diseases (INDs)." (PMID 19662226, 2007). "The CC chemokine receptors CCR1, CCR2 and CCR5 are critical for the recruitment of mononuclear phagocytes to the central nervous system (CNS) in multiple sclerosis (MS) and other neuroinflammatory diseases." (PMID 17484785, 2007).